HMX2 (H6 family homeobox 2)
Description:
Transcription factor involved in specification of neuronal cell types and which is required for inner ear and hypothalamus development.
Synonyms: NKX5-2; H6L
Tractability: PROTAC: ubiquitination databases record sites on it.
Gene: Protein-coding gene on chromosome 10 (123,148,136 to 123,150,672, forward strand). Ensembl gene ENSG00000188816.
Subcellular location: Nucleus
Gene Ontology:
Molecular function: sequence-specific double-stranded DNA binding; DNA-binding transcription factor activity, RNA polymerase II-specific; RNA polymerase II transcription regulatory region sequence-specific DNA binding; DNA binding
Biological process: regulation of transcription by RNA polymerase II; regulation of DNA-templated transcription
Cellular component: chromatin; nucleus
Genetic constraint (gnomAD): Loss-of-function variants: 15 observed, 19.03 expected, observed/expected ratio (o/e) 0.79, 90% interval 0.53 to 1.21. The upper end of that interval is the gene's LOEUF score, 1.21, which puts it in group 5 of 6, group 1 being the genes least tolerant of losing a copy. Missense variants: 440 observed, 374.96 expected, observed/expected ratio (o/e) 1.17, 90% interval 1.09 to 1.27. Synonymous variants: 193 observed, 175.57 expected, observed/expected ratio (o/e) 1.1, 90% interval 0.98 to 1.24.
Homologues: Orthologues: chimpanzee HMX2 (99% identical), macaque HMX2 (98% identical), pig HMX2 (96% identical), dog HMX2 (95% identical), rat Hmx2 (94% identical), guinea pig HMX2 (94% identical), mouse Hmx2 (94% identical), rabbit HMX2 (94% identical), zebrafish hmx2 (64% identical), tropical clawed frog hmx2 (59% identical). Paralogues in human: HMX3 (41% identical), HMX1 (35% identical), HOXA9 (19% identical).
Diseases named in the same sentence as HMX2 in open-access papers:
HMX2 is named in the same sentence as 17 diseases in open-access papers, as found by Europe PMC text mining. Sharing a sentence is not in itself a finding about the gene and the disease. The quoted sentences say what the papers report.
deafness (2 papers, 2013 to 2020). An inherited or acquired condition characterized by the complete loss of the ability to hear from one or both ears. "Their absence, together with the reduced expression of Hmx3, Hmx2 and Nkx1.2, which are located at the same chromosomal region, causes deafness and vestibular problems both in mice and humans." (PMID 23457544, 2013). "Mutations or loss of NKL homeobox gene expression is associated with corresponding developmental defects: aberrations of HMX1 result in malformation of the outer ear and those of HMX2/3 in inner ear defects and deafness." (PMID 33048949, 2020).
myelodysplastic syndrome (2 papers, 2020 to 2021). A clonal hematopoietic disorder characterized by dysplasia and ineffective hematopoiesis in one or more of the hematopoietic cell lines. "However, HMX2 and HMX3 are aberrantly expressed in AML and the activity of HMX1 was detected in subsets of myelodysplastic syndrome (MDS) patients." (PMID 33921702, 2021).
chronic lymphoid leukemia (1 paper, 2020). "Aberrant expression of HMX2 and/or HMX3 was also detected in a few lymphoid cell lines derived from B-cell precursor leukemia, chronic lymphoid leukemia and hairy cell leukemia, also indicating deregulation of these genes in some B-lymphoid malignancies." (PMID 33048949, 2020).
HIV-1 infection (1 paper, 2023). The type species of lentivirus and the etiologic agent of acquired immunodeficiency syndrome (AIDS). "Lastly, hMX2 has been proposed to restrict HIV-1 infection by an alternative mechanism involving the inhibition of the viral Rev protein." (PMID 37243034, 2023). "Similarly, it is proposed that cleavage and polyadenylation factor 6 (CPSF6) work alongside hMX2 to inhibit HIV-1 infection." (PMID 37243034, 2023). "However, oligomerization to structures larger than dimers seems to enhance the antiviral activity of hMX2, since interface I, III, and IV mutants often show weaker inhibition of HIV-1 infection compared to wild-type proteins." (PMID 37243034, 2023). "In fact, the overexpression of hMX2∆1-25 damped the IFN-imposed HIV-1 restriction on parental U87-MG cells but not on cells where hMX2 was depleted, indicating that hMX2∆1-25 negatively regulates the long isoform antiviral activity and, concomitantly, the type I IFN block to HIV-1 infection." (PMID 37243034, 2023).
sensorineural hearing loss (1 paper, 2019). "In humans, HMX3 and HMX2 are located together, close to FGFR4, on chromosome 10; hemizygous microdeletions that remove all three genes are thought to be causative for syndromes characterised by inner ear morphological anomalies, vestibular dysfunction and sensorineural hearing loss." (PMID 31022185, 2019).
viral infection (1 paper, 2023). "hMX1 exploits its GTPase activity to inhibit viral infection, and this led to an analysis of the antiviral activity of GTPase-deficient hMX2 mutants." (PMID 37243034, 2023). "In contrast, inhibition of HBV requires oligomers larger than dimers, which again highlights the various mechanisms employed by hMX2 to block viral infection." (PMID 37243034, 2023). "What is clear from all these works is that hMX2 exploits nuclear pore proteins to inhibit viral infection, with the interesting possibility of being able to use different subsets of NUPs, depending on the nature of the nuclear pore." (PMID 37243034, 2023). "This early failure to inhibit viral infection stuck with hMX2 for over 20 years, being largely considered devoid of antiviral activity." (PMID 37243034, 2023).
cancer (4 papers, 2010 to 2025). A tumor composed of atypical neoplastic, often pleomorphic cells that invade other tissues. "Analyzing gene expression and prognostic value in TCGA-COAD, we found that TCMM40L, SLC8A1, PPP1R3C, P2RX1 and HMX2 were significantly downregulated in cancer tissues." (PMID 40263288, 2025). "Five of the DMRs showed very low frequencies of heterogeneous methylation (for example, TITF1 and HMX2 with 65% and 87% of the cancer samples, respectively, showing the presence of full methylation of both alleles)." (PMID 24490656, 2014). "Besides being involved in morphogenesis HMX2, like HAND1, is repressed in cancer and induction seems to be involved in inhibition of proliferation." (PMID 23969837, 2013).
infection (1 paper, 2023). The state of being infected such as from the introduction of a foreign agent such as serum, vaccine, antigenic substance or organism. "This is translated into increased infection on hMX2-expressing HeLa cells when CPSF6 is depleted with small interfering RNAs (siRNAs)." (PMID 37243034, 2023). "In fact, an interesting model has been proposed wherein the CA conformation, affected by the interaction with different cellular factors during infection, dictates sensitivity to hMX2." (PMID 37243034, 2023). "However, in all cases, hMX2 inhibition seems to occur shortly after infection by inhibiting RNA replication of HCV and hepatitis B virus (HBV) or by blocking the nuclear import of viral replication complexes in the case of herpesviruses and retroviruses." (PMID 37243034, 2023). "Although the mechanism of this dependence is not understood, we know that hMX2 does not bind to the same CA surface as CypA, and that the CypA requirement is time-dependent since adding CSA at 12 h post-infection no longer had an effect on hMX2 inhibitory activity." (PMID 37243034, 2023). "Schilling and colleagues found that mutant T151A inhibited HSV-1 and MCMV replication (an alpha- and betaherpesvirus, respectively) but not infection by murine gamma herpesvirus 68 (MHV68, a gammaherpesvirus), pointing to different hMX2 requirements for the inhibition of distinct herpesviruses." (PMID 37243034, 2023).
tumor (1 paper, 2020). "In contrast, frequent HMX2 expression was detected in 13/42 (31.0%) AML patients with KMT2A-rearrangements (GSE19577), demonstrating high incidence in this tumor subtype." (PMID 33048949, 2020).
HMX2 also shares sentences with these, for which no sentence is quoted: acute myeloid leukemia (1 paper); fatty liver disease (1); hairy cell leukemia (1); head and neck squamous cell carcinoma (1); leukemia (1); Meniere disease (1); neurodevelopmental disorder (1); thyroid cancer (1).